GGNBP2 (gametogenetin binding protein 2)
Description:
May be involved in spermatogenesis.
Synonyms: LCRG1; LZK1; ZNF403; ZFP403; FLJ22561; FLJ21230; DIF-3; DIF3
Tractability: PROTAC: ubiquitination databases record sites on it.
Gene: Protein-coding gene on chromosome 17 (36,544,888 to 36,589,848, forward strand). Ensembl gene ENSG00000278311.
Subcellular location: Cytoplasmic vesicle
Subcellular location (Human Protein Atlas): Endoplasmic reticulum
Gene Ontology:
Cellular component: cytoplasm; nucleus; cytoplasmic vesicle
Genetic constraint (gnomAD): Loss-of-function variants: 6 observed, 58.94 expected, observed/expected ratio (o/e) 0.1, 90% interval 0.055 to 0.2. The upper end of that interval is the gene's LOEUF score, 0.2, which puts it in group 1 of 6, group 1 being the genes least tolerant of losing a copy. Missense variants: 445 observed, 670.48 expected, observed/expected ratio (o/e) 0.66, 90% interval 0.61 to 0.72. Synonymous variants: 217 observed, 221.56 expected, observed/expected ratio (o/e) 0.98, 90% interval 0.88 to 1.1.
Homologues: Orthologues: chimpanzee GGNBP2 (100% identical), macaque GGNBP2 (99% identical), pig GGNBP2 (99% identical), dog GGNBP2 (98% identical), guinea pig GGNBP2 (97% identical), rat Ggnbp2 (97% identical), mouse Ggnbp2 (96% identical), rabbit GGNBP2 (89% identical), zebrafish ggnbp2 (65% identical), tropical clawed frog ggnbp2 (60% identical), Drosophila melanogaster CG2182 (32% identical).
Diseases named in the same sentence as GGNBP2 in open-access papers:
GGNBP2 is named in the same sentence as 19 diseases in open-access papers, as found by Europe PMC text mining. Sharing a sentence is not in itself a finding about the gene and the disease. The quoted sentences say what the papers report.
intrahepatic cholangiocarcinoma (4 papers, 2023 to 2024). A carcinoma that arises from the intrahepatic bile duct epithelium in any site of the intrahepatic biliary tree. "A recent study showed that circGGNBP2 expression was increased in intrahepatic cholangiocarcinoma tissues and promoted the proliferation and metastasis of intrahepatic cholangiocarcinoma cells by encoding the GGNBP2‐184aa protein." (PMID 37070530, 2023). "In intrahepatic cholangiocarcinoma (ICC), IL-6 increases the expression of circRNA GGNBP2 to encode the protein cGGNBP2-184aa, which in turn forms a positive feedback loop of IL-6/cGGNBP2-184aa/STAT3 to facilitate ICC progression." (PMID 38890694, 2024). "Studies have shown that in intrahepatic cholangiocarcinoma (ICC) cells, IL-6 induces the expression of cyclic RNA (circRNA) GGNBP2 (cGGNBP2)." (PMID 39906665, 2024).
breast carcinoma (2 papers, 2019 to 2023). "The GGNBP2 gene codes for a protein that interacts with gametogenetin during spermatogenesis; the protein is also associated with amyotrophic lateral sclerosis (ALS), ovarian cancer, breast cancer and chromosome 17Q12 deletion syndrome." (PMID 37026480, 2023). "A tumor suppressor gene, gametogenetin-binding protein 2 (GGNBP2) has been found to inhibit breast cancer cell proliferation and induce apoptosis, independent of ER expression." (PMID 31088482, 2019).
male infertility (2 papers, 2017 to 2018). The inability of the male to effect fertilization of an ovum after a specified period of unprotected intercourse. "The results demonstrate that loss of Ggnbp2 increases DNA DSBs and compromises DSB repair during male meiosis, suggesting that male infertility in Ggnbp2KO mice is partially attributed to the role of GGNBP2 in spermatocyte meiosis." (PMID 30055035, 2018).
astrocytoma (1 paper, 2023). "Compared to the other tumor groups, high expressions of TSGA10 and GGNBP2 were observed in astrocytoma’s grade 2." (PMID 36860313, 2023). "Accordingly, understanding their expression levels may be informative relative to the influence of the TSGA10 and GGNBP2 genes in astrocytoma and, consequently, in patients’ prognoses." (PMID 36860313, 2023).
brain tumor (1 paper, 2023). "This article reports on the different expression patterns of TSGA10 and GGNBP2 transcript variants with different 5′UTR sequences in human brain tumor samples." (PMID 36860313, 2023). "We used RT-PCR to identify the expression pattern of TSGA10 and GGNBP2 transcript variants and the characteristics of their expression profiles in different brain tumor samples." (PMID 36860313, 2023). "TSGA10 and GGNBP2 gene variants expression in 30 brain tumor samples." (PMID 36860313, 2023). "Although our study showed the expression of different transcript variants of TSGA10 and GGNBP2 genes in brain tumor samples, several limitations could affect this study." (PMID 36860313, 2023). "In addition, to validate our in-silico data analysis, RT-PCR was performed to determine the splicing variants of TSGA10 and GGNBP2 genes in testis and brain tumor samples." (PMID 36860313, 2023). "Therefore, decreased amounts of TSGA10 and GGNBP2 as potential tumor suppressor proteins, especially in high-grade brain tumors, may cause cancer development by angiogenesis and metastasis." (PMID 36860313, 2023). "The present study undertook a microarray analysis and found that differential expression of TSGA10 and GGNBP2 were deregulated in brain tumor samples." (PMID 36860313, 2023). "Public data on brain tumor microarray datasets in GEO were analyzed with R software to evaluate the expression levels of TSGA10 and GGNBP2 genes (the Pheatmap package in R was also used to plot DEGs in a heat map)." (PMID 36860313, 2023). "We identified that the TSGA10 and GGNBP2 were expressed in all of the brain tumor and testicular tissue samples, but the expression of the transcript variants with longer 5′UTR was reduced in brain tumor samples, unlike the testis sample." (PMID 36860313, 2023).
esophageal squamous cell carcinoma (1 paper, 2024). Esophageal squamous cell carcinoma (ESCC) is a type of esophageal carcinoma (EC) that can affect any part of the esophagus, but is usually located in the upper or middle third. "Wang and colleagues reported that FBXO45 accelerated tumor malignant progression via regulation of ubiquitination and degradation of GGNBP2 in esophageal squamous cell carcinoma." (PMID 38773471, 2024).
glioma (1 paper, 2023). A benign or malignant brain and spinal cord tumor that arises from glial cells (astrocytes, oligodendrocytes, ependymal cells). "Accordingly, GGNBP2 acted as a tumor suppressor in patients with glioma and was suggested as a potential therapeutic method." (PMID 36860313, 2023).
medulloblastoma (1 paper, 2023). A malignant, invasive embryonal neoplasm arising from the cerebellum. "Higher-grade BTs display a sharp decrease in TSGA10 and GGNBP2 transcripts, especially in medulloblastoma grade IV, given that TSGA10 and GGNBP2 expressions decrease in higher grades of BTs." (PMID 36860313, 2023).
Obesity (1 paper, 2023). Accumulation of substantial excess body fat. "SNP rs12951387 is located in GGNBP2, encoding a gametogenetin-binding protein associated with obesity." (PMID 37759214, 2023).
viral infection (1 paper, 2020). "Particularly, the biological process related to the interaction of p7-CNTN1/GGNBP2 will be further explored, because there is less supporting evidence for effect of CNTN1 and GGNBP2 on viral infection in the literature." (PMID 33329485, 2020).
tumor (7 papers, 2013 to 2024). "The findings suggest that the TSGA10 and GGNBP2 transcript variants might present a functional role, altering the expression patterns of these genes, thereby increasing tumor growth and stimulating malignancy traits." (PMID 36860313, 2023). "The overexpression of GGNBP2 decreases tumor cell proliferation, migration, invasion, angiogenesis, and metastasis of human cancers and arrest in the G1 phase of the cell cycle." (PMID 36860313, 2023). "Meanwhile, we noticed that GGNBP2 is an important tumor suppresser involved in several kinds of cancers." (PMID 33541344, 2021). "Gametogenetin Binding Protein 2 (GGNBP2) was identified as a tumor suppressor and verified as such by several studies." (PMID 28592902, 2017). "Lan8 reported that GGNBP2 was a novel breast cancer tumor suppressor functioning as a nuclear receptor corepressor to inhibit ERα activity and tumorigenesis." (PMID 28592902, 2017). "GGNBP2 is also a tumour suppressor involved in several kinds of cancers." (PMID 34945679, 2021). "The expression of GGNBP2 was significantly upregulated only in the GSE35493 dataset and in GMB tumor samples with a log2 fold change of 0.88." (PMID 36860313, 2023). "Regarding the transcript expression patterns, the relative mRNA expression of TSGA10 and GGNBP2 genes in the BT samples differed from normal testicular tissue; accordingly, the transcripts have a shorter 5′UTR sequence in tumor samples." (PMID 36860313, 2023).
cancer (6 papers, 2017 to 2023). A tumor composed of atypical neoplastic, often pleomorphic cells that invade other tissues. "Gametogenetin binding protein 2 (GGNBP2) is a ubiquitously expressed gene involved in spermatogenesis and the regulation of cancer cell proliferation and metastasis." (PMID 37152278, 2023). "This study analyzed the 5′UTR region of TSGA10 and GGNBP2, considering the significance of the regulatory effects of 5′UTR and unclear mechanisms regulating the expression of TSGA10 and GGNBP2 in normal and cancer cells." (PMID 36860313, 2023). "Therefore, GGNBP2 might act as potential genetic links between ALS and cancer." (PMID 33541344, 2021).
GGNBP2 also shares sentences with these, for which no sentence is quoted: amyotrophic lateral sclerosis (1 paper); autism (1); diabetes (1); Infertility (1); language delay (1); laryngeal carcinoma (1); ovarian carcinoma (1).